VWF (von Willebrand factor)
Diseases named in the same sentence as VWF in open-access papers (continued):
Sharing a sentence is not in itself a finding about the gene and the disease.
Stroke (continued). "In the current study, Paeoniflorin administration promotes von Willebrand factor (an endothelia cell marker) and doublecortin (a neuroblasts marker) expression compared with control, suggesting that Paeoniflorin facilitates neurogenesis and vasculogenesis in rat stroke model." (PMID 34123580, 2021). "Compared with control, Paeoniflorin administration facilitated von Willebrand factor (an endothelia cell marker) and doublecortin (a neuroblasts marker) expression, indicating that Paeoniflorin contributed to neurogenesis and vasculogenesis in rat stroke model." (PMID 34123580, 2021). "Thus, the miR-100, miR-424, miR-15a, and VWF inside the EVs of our study patients with CSC stroke could be promoting angiogenesis and new vessel formation after stroke." (PMID 34356850, 2021). "Our data suggest a VWF‐mediated role for MMP‐13 in the recruitment of platelets to the site of vascular injury and may provide new insights into the association of MMP‐13 in atherothrombotic and stroke pathologies." (PMID 31894636, 2020). "Furthermore, there are premises suggesting value of some biomarkers in the diagnosis of specific stroke types, such as cardioembolic stroke (vWF, TNFα), hemorrhagic stroke (GFAP, MMP-9), large- and small-artery disease (IL-6; TNFα), or lacunar stroke (Glu, GABA)." (PMID 31701356, 2020). "At least in preclinical animal research, targeting VWF via anti-VWF-GPIbα strategies or recombinant ADAMTS13 did not increase the risk of intracranial hemorrhaging in murine stroke models, even when combined with tissue-plasminogen activator or when treatment was delayed." (PMID 31921147, 2019). "In further sensitivity analyses, associations of VWF and ADAMTS13 with dementia were similar for Alzheimer’s disease only, and unaffected by excluding those with prevalent cardiovascular disease and censoring participants at time of myocardial infarction or stroke during follow-up." (PMID 29615758, 2018). "In this context, the identification of vWF-rich thrombi by computed tomography or magnetic resonance imaging to guide treatment could become an interesting future approach for more individualized stroke therapy." (PMID 29847840, 2018). "Here, we could not find any association of FVIII/VWF levels with the subtype of stroke as classified by the TOAST criteria." (PMID 29410644, 2017). "In this view, VWF may become a hopeful target in stroke management." (PMID 28634421, 2017). "While clots with huge amounts of vWF seem to be associated with a high National Institute of Health Stroke Scale score at admission, histologic findings could not predict the clinical outcome at discharge." (PMID 26927082, 2016). "Despite a few studies that could not find an association between VWF levels and stroke risk or increased coagulability, the vast majority of prospective studies point towards high VWF levels as risk factor also for AIS." (PMID 24937073, 2014). "Preventing platelet adhesion and subsequent aggregation at sites of vascular injury by blocking the VWF/GPIb interaction represent an attractive target for the treatment of important human diseases including thrombotic thrombocytopenic purpura, acute coronary syndrome, and stroke." (PMID 24019925, 2013). "The density of blood vessels as monitored by vWF immunoreactivity was significantly higher in the brains of rats that received three million In-111-labeled hUTC compared to In-111 oxine treated group after 12 weeks following the administration of In-111 labeled hUTC 48 hrs after stroke." (PMID 23217090, 2012). "We show that SARS‐CoV2 infections drive a VWF/ADAMTS13 axis imbalance, inducing an increase in tPA while decreasing FIX, MMP‐2, and sICAM‐1 post‐stroke." (PMID 39972966, 2025).
Stroke (continued). "Moreover, characterizing how VWF, NETs, and other key indicators evolve throughout stroke progression represents an important avenue for future research, as it could deepen our understanding of the relationship between the pathophysiology of cerebral infarctio n and clinical biomarkers." (PMID 40625905, 2025). "The outcomes of prospective studies indicate that, in patients with non-valvular AF, high vWF plasma concentrations, in conjunction with established cardiovascular risk factors, might more accurately predict clinical outcomes, such as stroke or all-cause death." (PMID 38397876, 2024). "Recent studies claim that the outer layer of thrombi retrieved from patients with stroke is composed mainly of RBC, fibrin, von Willebrand Factor, and leukocytes that all play a role against r-tPA." (PMID 38465650, 2024). "Four proteins [ceruloplasmin, alpha-1-antitrypsin (SERPINA1), von Willebrand factor (vWF), and coagulation factor XIII B chain (F13B)] commonly differentiated total stroke, IS, and ICH from healthy control subjects." (PMID 36237606, 2022). "In a prospective study, patients with stroke and TIA represented an obvious elevation in vWF levels more prominently in patients with a recent symptomatic history of carotid stenosis." (PMID 35207321, 2022). "No sex differences were found for glutamate and phospholipase A2 (PLA2) within 72h after stroke, thromboxane 2 (TXA2), prostaglandin I2 (PGI2), adenosine diphosphate (ADP) within 2 weeks after stroke, and vWF 3 months after stroke." (PMID 34858141, 2021). "Our data indicate that 3 μg/kg VT treatment in T1DM stroke rats significantly increases the number of vessels (vWF, p < 0.05) in the IBZ compared to PBS‐treated T1DM stroke rats." (PMID 33346402, 2021). "The combination of S100B, B-type neurotrophic growth factor (BNGF), von Willebrand factor (vWF), MMP-9, and monocyte chemotactic protein-1 (MCP-1) provided diagnosis of stroke within 12 h after symptom onset with a 91% sensitivity and a 97% specificity." (PMID 33633673, 2021). "Individuals with HA have normal levels of circulating VWF, thus prolonging VWF half-life to also increase FVIII half-life could raise the level of circulating VWF in these individuals, and therefore increase the risk of arterial diseases such as heart attack or stroke." (PMID 34521404, 2021). "In experimental stroke models, N-Acetylcysteine, a mucolytic drug, and ADAMTS13, a vWF cleaving enzyme, have shown to effectively dissolve tPA resistant thrombi and reduce cerebral infarct size." (PMID 33732203, 2021). "Although the anti-vWF nanobody caplacizumab was initially approved in 2018 as treatment for thrombotic thrombocytopenic purpura, it was also shown to be an effective therapy in a stroke model using guinea pigs, indicating that it might also be beneficial in stroke therapy." (PMID 31736950, 2019). "Taken together, these data support the rationale that not only vWF levels, but also the vWF-modifying enzyme ADAMTS13 plays an important role in the development of first-ever stroke." (PMID 29847840, 2018). "In this study, we examined the levels of FVIII and VWF during thrombolysis in 131 consecutive AIS patients and studied the relationship between the hemostasis factor levels and stroke characteristics and therapy outcomes." (PMID 29410644, 2017). "Combination treatment of rt-PA with N-Acetylcysteine, a mucolytic drug with effects on cleavage of the von Willebrand Factor (VWF), exerts increased thrombolytic effects in a mouse model of stroke." (PMID 29232823, 2017). "More recently, Hanson and collaborators examined vWF levels in patients with CE, LAA SVD or UND stroke." (PMID 24527683, 2013). "Co-stainings with Occludin, Von-Willebrand Factor and CD34 demonstrated localization of SVCT2 in brain capillary endothelial cells in the ischemic area after stroke." (PMID 21347255, 2011).
Stroke (continued). "The SARS‐CoV2 positive IS cohort showed elevated plasma levels of VWF compared to both the non‐stroke control cohort and the SARS‐CoV2 negative IS cohort." (PMID 39972966, 2025). "However, the SARS‐CoV2 infection's contribution to any VWF/ADAMTS13 axis imbalance and the subsequent thromboinflammatory response post‐stroke remain poorly understood." (PMID 39972966, 2025). "Higher levels of vWF reflect activation of the endothelial system during a stroke, while a lack of vWF expression indicates impaired cerebral endothelial function." (PMID 40376151, 2025). "The temporal evolution of leukocyte levels, VWF, and NETs during stroke progression are not examined." (PMID 40625905, 2025). "Additionally, targeting CD39, the NETs-vWF axis, PAD4, and NADPH oxidase, inhibiting CD147, and suppressing plasma kallikrein all have inhibitory effects on the formation of stroke." (PMID 39287275, 2024). "The key finding from this study is that whilst CRP retained significant independent association with mortality in the subgroup of patients with previous stroke, IL-6 and VWF did not." (PMID 35042473, 2022). "When separated by history of previous stroke, systemic and vascular inflammation (assessed by IL-6 and VWF respectively) no longer significantly contributed to the risk of death." (PMID 35042473, 2022). "In the general population, most previous studies focused on the association between VWF, ADAMTS13 and non-fatal cardiovascular outcomes (myocardial infarction or stroke)." (PMID 34134634, 2021). "Alarmingly, a young and asymptomatic SARS-CoV-2-infected patient who showed increased FVIII and vWF levels without any sign of hyperinflammatory state or blood coagulation activation suffered a stroke." (PMID 33562030, 2021). "Not surprisingly, different studies have identified VWF as an important constituent of stroke thrombi with a direct impact on thrombolysis." (PMID 33692737, 2021). "Intriguingly, increased VWF activity and/or reduced ADAMTS13 activity are associated not only with higher stroke occurrence, but also with worse long-term stroke outcomes." (PMID 31921147, 2019). "For example, vWF levels correlate with C-reactive protein (CRP) levels on admission;37however, data are conflicting concerning persisting elevation of vWF in the late phase after stroke." (PMID 29847840, 2018). "vWF levels were measured at the time of first ischaemic event and therefore no clear assumption can be made if vWF determines post-stroke morbidity and mortality as well as recurrence or only predicts outcome in stroke patients." (PMID 29847840, 2018). "Moreover, VWF and ADAMTS13 have been recently proposed as prognostic biomarkers in cardiovascular, metabolic, and inflammatory diseases, such as diabetes, stroke, myocardial infarction, and sepsis." (PMID 28634421, 2017). "Furthermore, when assessing the VWF:ADAMTS13 ratios, an even greater difference was revealed between stroke patients (2.7 ± 1.9), HV (1.1 ± 0.5) and CCD patients (1.7 ± 0.7)." (PMID 28591212, 2017). "A positive correlation between VAT and vWF has been reported in obese women, but to the best of our knowledge, no studies in stroke patients have been published." (PMID 28570705, 2017). "However, also a persistent elevation of vWF has been reported several months after AMI and stroke, indicative of chronic endothelial activation." (PMID 28570705, 2017). "Furthermore, engagement of GPIb-IX-V by von Willebrand factor (VWF) mediates platelet adhesion to damaged vessels and triggers platelet activation and thrombus formation in heart attacks and stroke." (PMID 27036108, 2016). "Spontaneous intracerebral haemorrhage (ICH) is the most devastating stroke subtype and has no proven treatment. von Willebrand factor (VWF) has recently been demonstrated to promote inflammation processes." (PMID 27782211, 2016).
Stroke (continued). "These promising data confirm that VWF/GPIbα interaction is essential for platelet adhesion but also for initial thrombus formation in stroke and showed that as opposed to an αIIbβ3 inhibitor (tirofiban), VWF/GPIbα blockade does not lead to hemorrhage." (PMID 25297919, 2015). "Thus, we used antibodies against Von-Willebrand Factor (VWF) and CD34 to confirm endothelial localization of SVCT2 after stroke." (PMID 21347255, 2011). "After stroke, SVCT2 was localized specifically in brain capillary endothelial cells immunoreactive for the tight junction marker Occludin and the endothelial cell markers VWF and CD34." (PMID 21347255, 2011). "Therefore, the patients experiencing s‐HT do not inherently present with low vWF levels prior to the stroke event." (PMID 40135640, 2025). "Overall, our study has highlighted that the thromboinflammatory response post‐stroke is affected by the preceding SARS‐CoV2 infection by enhancing the VWF/ADAMTS13 axis imbalance and does not elevate to the same magnitude the protein levels of MMP‐2, sICAM‐1, and FIX." (PMID 39972966, 2025). "However, in a post-acute phase study on children with ischemic stroke, vWF plasma levels in stroke patients were not meaningfully different from the control group and were excluded as a risk factor for ischemic stroke." (PMID 35207321, 2022). "Hence, platelets and VWF most likely contribute to stroke progression in a way that is not strictly related to thrombus formation." (PMID 31921147, 2019). "As GoF ADAMTS‐13 shows an increased ability to dissolve VWF/platelet‐rich aggregates in vitro, we hypothesized that it may exert a more pronounced protective effect than WT ADAMTS‐13 in an experimental model of stroke." (PMID 30152919, 2018). "The relationship of VAT to vWF has not been previously investigated in stroke patients." (PMID 28570705, 2017). "Importantly, stroke severity (NIHSS>15 points), CRP levels at admission, and the intake of platelet inhibitors in the days before blood withdrawal each independently predicted VWF levels." (PMID 24937073, 2014). "Since VWF is the main ligand of GPIbα on platelets, our data support the notion of a pathophysiological role for the GPIbα-VWF interaction in stroke, although we can not rule out that other GPIbα-mediated interactions are also important and abrogated in GPIbα/IL4Rα mice." (PMID 21914206, 2011). "In other words, in human endothelial cells the viral S protein evokes a disbalance in the vWF:ADAMTS-13 ratio which may favor thrombi formation, similar to that observed in certain pro-coagulant and pro-thrombotic conditions such as thrombotic thrombocytopenic purpura or stroke." (PMID 38225643, 2024). "Thus, our finding of significantly elevated vWF, D-dimer and TAT levels among children with SCD who had a higher risk for stroke was not surprising because of these well-established association in non-SCD related cases of cerebrovascular and cardiovascular diseases." (PMID 26305570, 2015). "CCR3 and Prussian blue staining significantly increased in rat brain sections following stroke at 30 days, but not at 3 days, and co-staining with CCR3 and vWF antibodies demonstrated overlapping expression." (PMID 38332938, 2024). "A study of 263 thrombolysed acute ischaemic stroke patients further supports these findings, with vWF levels found comparable between patients with WMH lesions, cerebral atrophy or lacunes visible on CT compared to those without at the time of stroke onset." (PMID 37685924, 2023). "The inflammatory involvement of platelets in stroke is thought to be mediated via GPVI, as well as the VWF A1-GPIbα axis, but not αIIbβ3." (PMID 36674781, 2023). "Patients who died because of stroke during the follow-up time had higher levels of D-dimer, endostatin, IL-6, NT-proBNP, VAP-1, vWF, and TNF-R1 than patients who did not die." (PMID 33578805, 2021).
Stroke (continued). "We then compared the plasma levels of D-dimer, OPN, OPG, vWF, and ADAMTS13 in LVO and non-LVO patients; the plasma levels of GFAP were compared in hemorrhagic vs. ischemic stroke and non-stroke patients." (PMID 34206615, 2021). "Based on IDI and NRI, the addition of vWF to CHA2DS2-VASc statistically improved its predictive value for cardiovascular events, stroke and cardiovascular mortality, but C-indexes were not significantly different and remained modest (approx. 0.6)." (PMID 28134282, 2017). "The time point of blood withdrawal for the stroke patients (days 0, 1 and 3) did not influence ADAMTS13 levels (p = 0.630) or the VWF:ADAMTS13 ratio (p = 0.990)." (PMID 28591212, 2017). "In subjects with CEI subtype and metabolic syndrome, PWV was more significantly and positively related to vWF but not with TNF-α, CRP, IL-6, IL-1β and PAI-1 compared to subjects without metabolic syndrome and the same subtype of stroke." (PMID 24571954, 2014). "In subjects with stroke classified as LAAS and metabolic syndrome, PWV was more significantly and positively related to CRP, IL-1β, IL-6, TNF-α, vWF and PAI-1 compared to subjects without metabolic syndrome and the same subtype of stroke." (PMID 24571954, 2014). "Additionally, a case-controlled study in young HIV positive stroke patients demonstrated that elevated levels of VWF in comparison with both uninfected and HIV-infected patients without stroke group." (PMID 32722629, 2020). "Among subjects with lacunar subtype and metabolic syndrome, PWV (after correction for age and gender) was more significantly and positively related to CRP, IL-1β, IL-6, TNF-α, vWF and PAI-1 compared to subjects without metabolic syndrome and the same subtype of stroke." (PMID 24571954, 2014).